GPX4 (glutathione peroxidase 4)
Diseases named in the same sentence as GPX4 in open-access papers (continued):
Sharing a sentence is not in itself a finding about the gene and the disease.
lung cancer (continued). "Mechanistically, Huaier simultaneously and independently downregulates the antioxidant pathway SLC7A11/GPX4 and elevates intracellular iron levels through NCOA4-mediated ferritinophagy degradation of FTH1 in lung cancer cells." (PMID 40623982, 2025). "Curcumin is the main phenolic pigment extracted from turmeric (the powdery rhizome of turmeric), which inhibits the expression of GPX4 and FSP1 in lung cancer cells, disrupting GPX4 activity in glioblastoma cells and stimulating ferroptosis." (PMID 38783959, 2024). "In lung cancer, resistance to PDT can occur due to the up-regulation of GPX4, which degrades ROS essential for the therapy's effectiveness." (PMID 39104501, 2024). "Targeting GPX4 with high expression in LUAD tissues can regulate ferroptosis, thereby affecting the occurrence and progression of lung cancer." (PMID 39400975, 2024). "Curcumin promotes ferroptosis, thereby inhibiting lung cancer tumor growth, by upregulating ACSL4 and downregulating ferroptosis-inhibiting genes (SLC7A11 and GPX4)." (PMID 38892270, 2024). "By combining DHA with PDT, the inhibition of GPX4 allows for the accumulation of ROS during PDT, potentially enhancing its anti-cancer efficacy in lung cancer cells." (PMID 39104501, 2024). "Juglone treatment increased MDA level but suppressed GPX4 and SOD activities in lung carcinoma cells compared with that in the control group." (PMID 38814975, 2024). "Glutathione peroxidase 4 (GPX4) determines the sensitivity of lung cancer cells to etoposide-induced ferroptosis, and NEDD4L can ubiquitinate GPX4, resulting in its subsequent degradation." (PMID 38027016, 2023). "Orlistat is currently the only OTC weight-loss drug in the world, which can inhibit the progression of lung cancer by targeting FAF2, significantly inhibit GPX4 expression, and induce lipid peroxidation in cells." (PMID 37005430, 2023). "In the ferroptosis related studies of lung cancer, CAP can inhibit the proliferation of A549 and NCI-H23 cells and induce ferroptosis by inactivating SLC7A11/GPX4 signaling pathway." (PMID 37005430, 2023). "To verify the roles of Notch3 in tumorigenesis and the relationship of Notch3 with GPX4 and PRDX6, we established an in vivo xenograft model using Notch3 knockdown lung cancer cells." (PMID 35258176, 2022). "After knockout of KEAP1 in lung cancer cells, the authors found upregulation of NRF2 and SLC7A11 expectedly, but the GPX4 level even decreased in these lung cancer cell lines." (PMID 36264074, 2022). "The in vivo results also displayed stronger ferroptosis in lung cancer cell-bearing mice that received DHA treatment, as indicated by the augmented expression of COX-2 and reduced expression of GPX4." (PMID 36034842, 2022). "Our study found that both SLC7A11 and GPX4 were overexpressed in CRC, and SLC7A11 was highly expressed in lung cancer by analyzing TIMER and Oncomine databases." (PMID 34722530, 2021). "Our results showed that both SLC7A11 and GPX4 were overexpressed in colorectal cancer, and SLC7A11 was overexpressed in lung cancer." (PMID 34722530, 2021). "For this purpose, we used cell lines that are resistant to ferroptosis induced by GPX4 inhibition, including Hs578t cells, the glioblastoma cell line SF295, and the non‐small cell lung cancer cell line NCI H1975." (PMID 34223704, 2021). "Activation of NFE2L2 negatively regulates ferroptosis in various cells (including lung cancer cells) by upregulating various target genes, e.g. heme oxygenase 1 (HMOX1), SLC7A11, GPX4, and superoxide dismutase 2 (SOD2)." (PMID 34742351, 2021). "For instance, a study in A549 and H1299 lung cancer cells reported that OA treatment led to the upregulation of ACSL4 and downregulation of GPX4, accompanied by elevated ROS levels and enhanced lipid peroxidation, ultimately accelerating ferroptosis cell death." (PMID 41301966, 2025).
lung cancer (continued). "Additionally, C11 staining, GPX4 expression detection, and tissue lipid peroxidation staining confirmed that NR2 can induce ferroptosis in lung cancer cells." (PMID 41242017, 2025). "miR-101-3p is underexpressed in lung cancer tissues and cells used for promoting proliferation, which is reversed by miR-101-3p overexpression restoring the ferroptosis of lung cancer cells by targeting TBLR1 to downregulate GPX4." (PMID 38892270, 2024). "This study confirmed that OA could inhibit SDC4 expression and promote the occurrence of ferroptosis in A549 cells and H1299 cells through the GPX4/ACSL4 pathway, providing an effective basis for the use of drugs targeting ferroptosis in lung cancer treatment." (PMID 39400975, 2024). "Likewise, in glioblastoma and lung cancer cells, DHA induced ferroptosis by inhibiting xCT/GPX4 axis in different ways, indicating that the mechanisms of DHA-induced ferroptosis in various cells were different." (PMID 37065442, 2023). "The growth of ferroptosis-resistant H460 lung cancer cells can only be reduced by double knockout of GPX4 and FSP1, but not by GPX4 single knockout in a preclinical tumor xenograft mouse model." (PMID 36445538, 2022). "There is no consensus on the relationship between GPX4 expression and patient survival in lung cancer." (PMID 36443446, 2022). "Interestingly, we showed that protein expression levels of NRF2 and glutathione peroxidase 4 (GPX4), a major scavenger of phospholipid peroxides, were both reduced in lung cancer cells after ZVI-NP treatment." (PMID 34093872, 2021). "We can conclude that FSP1 continue to promote the growth of H460 lung cancer tumors in vivo in the absence of GPX4." (PMID 34616505, 2021). "Notably, H460 lung cancer cells with high expression of FSP1 survived normally upon GPX4 knockout, whereas rapid death was observed in GPX4 and FSP1 double-knockout cells." (PMID 32908642, 2020). "The therapeutic relevance of targeting FSP1 is highlighted in certain contexts, such as Keap1-mutant lung cancers (e.g., H460, A549), where FSP1 is highly expressed and GPX4 levels are low, suggesting that FSP1 inhibition could be a particularly effective strategy in these tumors." (PMID 41471274, 2025). "To investigate the anticancer effect and mechanism of OA on lung cancer, we first stimulated lung cancer cells with OA in vitro and observed its changes and further analyzed the role of ferroptosis, the SDC4 gene, and the glutathione peroxidase 4 (GPX4)/ACSL4 signaling pathway." (PMID 39400975, 2024). "In summary, further study of the expression of m6A methylation-related molecules in lung cancer cells and the mechanism of ferroptosis regulation by m6A methylation-related molecules such as SLC7A11 and GPX4 may provide a new feasible pathway for the regulation of ferroptosis in lung cancer." (PMID 38515565, 2024). "Importantly, GPX4 was positively correlated with resistance of lung cancer cells to L-685458, lapatinib, paposilli, and topotecan, suggesting that targeting System Xc−/GSH/GPX4 axis could overcome drug resistance." (PMID 36105219, 2022). "Finally, the effect of EC on ferroptosis in lung cancer cells was tested, and the results revealed that EC treatment significantly increased the Fe2+ concentrations in H460 and H1299 cells while inhibiting the expression of the ferroptosis-related proteins SLC7A11, GPX4, and FTH1." (PMID 39480832, 2024). "In conclusion, our study demonstrated the adverse prognostic role of TNFSF11 in lung cancer, and also discovered a negative correlation between TNFSF11 and GPX4." (PMID 38594779, 2024). "In preclinical tumor xenograft mouse models, ferroptosis-resistant H460 lung cancer cells’ growth was only inhibited by a double knockout of GPX4 and FSP1, not by a single knockout of GPX4." (PMID 38206305, 2024).
lung cancer (continued). "Excitingly, the overexpression of STYK1 in lung cancer cell line SW900 upregulates GPX4 expression, promotes cell proliferation and attenuates ferroptosis-specific mitochondrial abnormalities, while downregulation of GPX4 exacerbates this attenuation without affecting cell proliferation." (PMID 37005430, 2023).
Sepsis (116 papers, 2019 to 2026). Sepsis is defined as life-threatening organ dysfunction caused by a dysregulated host response to infection. "For example, in bacterial and polymicrobial sepsis models (e.g., cecal ligation and puncture), markers of ferroptosis (lipid peroxidation, mitochondrial changes, loss of GPX4 activity) are elevated, and ferroptosis inhibitors (like Fer-1) reduce organ injury." (PMID 41516398, 2026). "While previous research has linked eCIRP to GPX4-mediated ferroptosis and impaired macrophage phagocytosis in sepsis, the upstream drivers of these effects have remained elusive." (PMID 41357225, 2025). "There were strong associations between sepsis events and the expression levels of GPX4 in classical and alternative monocytes, as well as PRDX4 in naïve CD4+ T cells and GR in naïve CD8+ T cells." (PMID 40593569, 2025). "Hepatic injury studies demonstrate that irisin effectively mitigates sepsis‐associated hepatocyte ferroptosis by regulating GPX4 expression levels." (PMID 40919133, 2025). "Sepsis-induced loss of Ras-associated protein 26 (Rab26) shifts macrophages from M1 to M2, worsening GPX4 loss and increasing ferroptosis risk." (PMID 41250137, 2025). "Downregulation of GPX4 expression in sepsis is closely associated with the exacerbation of oxidative damage." (PMID 41250137, 2025). "Our study demonstrated that ferroptosis-related protein markers ACSL4 and GPX4 possess significant diagnostic and differential diagnostic value in sepsis, including the ability to predict 28-day mortality in our study cohort." (PMID 40264754, 2025). "Future larger studies that incorporate repeated measurements and focus on specific pathogens are necessary to further clarify the multifaceted pathophysiological mechanisms underlying ACSL4 and GPX4 in sepsis." (PMID 40264754, 2025). "Others—Glutathione Peroxidase 4 (GPX4): A recent study in children investigated GPX4, which plays a crucial role in sepsis diagnosis and is associated with the disruption of oxidative balance, lipid peroxide accumulation, and ferroptosis." (PMID 40364014, 2025). "Although direct links between ferroptosis-related genes and sepsis are limited, the GPX4 rs713041 polymorphism affects endothelial function, potentially modulating ferroptosis sensitivity in sepsis." (PMID 41250137, 2025). "The results confirmed that serum levels of ACSL4 and GPX4 possess high diagnostic and differential diagnostic values for sepsis, comparable to the SOFA score, CRP, and PCT, and superior to the APACHE II score and GCS score." (PMID 40264754, 2025). "The loss of GPX4 function is linked to organ failure in sepsis and worsens the prognosis by damaging mitochondria." (PMID 40364014, 2025). "Irisin prevents sepsis-associated encephalopathy and cognitive dysfunction in diabetic encephalopathy by inhibiting ferroptosis through the activation of the Nrf2/GPX4 signaling axis." (PMID 39596528, 2024). "We subsequently demonstrated, for the first time, that PRDM16 exerts an inhibitory effect on ferroptosis to confer protection against sepsis-associated AKI by targeting the NRF2/GPX4 axis." (PMID 39549609, 2024). "Nobiletin was previously reported to mitigate sepsis-associated acute liver injury by inhibiting the NRF2/glutathione peroxidase 4 (GPX4)-mediated ferroptosis." (PMID 38570541, 2024). "In studies on sepsis, miRNA miR-125b-5p has been found to play an active role in inflammation, directly targeting Keap1 and reducing cell-death-induced inflammation through the Keap1/Nrf2/GPX4 pathway, thereby improving acute lung injury caused by sepsis." (PMID 37686375, 2023). "Our previous work confirmed that NETs induced METTL3‐mediated m6A modification of GPX4 via TLR9/MyD88/NF‐κB pathway in sepsis‐associated lung injury." (PMID 37715457, 2023). "The application of vitamin E, the caspase inhibitor Z-VAD-FMK or wedelolactone reduced the serum levels of proinflammatory factors and reversed the contribution of GPX4 deficiency to lethal sepsis in vivo." (PMID 36944609, 2023).
Sepsis (continued). "Gpx4 deficiency in myeloid cells was also shown to increase disease severity in a murine model of polymicrobial sepsis as a result of an enhanced lipid peroxidation–dependent caspase-11 activation and consequently gasdermin D–mediated pyroptosis." (PMID 36069923, 2022). "Another report showed that myeloid-specific deficiency of Gpx4 drove pyroptosis during polymicrobial sepsis." (PMID 34267193, 2021). "Accordingly, the conditional knockout of Gpx4 (Gpx4−/−Mye) in myeloid cells increases the risk of polymicrobial sepsis through the activation of caspase-11 inflammasome." (PMID 31440260, 2019). "In addition, GPX4 has strong diagnostic and differential diagnostic value in predicting sepsis outcomes and multiple organ dysfunction." (PMID 41250137, 2025). "GPX4-mediated cysteine metabolism is also involved in sepsis-associated myocardial injury." (PMID 40356926, 2025). "Targeting the GPX4 pathway may thus offer therapeutic potential for attenuating the severity of sepsis and its associated organ dysfunction." (PMID 40264754, 2025). "In sepsis models, poly (lactide-co-glycolic acid)-encapsulated FMN (PLGA-FMN) significantly upregulates PRDM16 expression and activates the NRF2/GPX4 pathway, effectively inhibiting ferroptosis and reducing sepsis-associated multiorgan injury, including lung damage." (PMID 41199815, 2025). "our findings suggest that melittin may be a potential therapeutic agent for the treatment of sepsis-associated acute kidney injury by inhibiting ferroptosis through the GPX4/NRF2 pathway." (PMID 38149613, 2024). "Additionally, in a murine model of ALI caused by sepsis via cecal ligation, ferroptosis marker GPX4 expression was downregulated, while MDA and iron ion levels increased." (PMID 39737174, 2024). "Furthermore, irisin was found to suppress ferroptosis and protect from sepsis-associated encephalopathy and liver injury in vivo and in vitro through the Nrf2/Glutathione peroxidase 4 (Nrf2/GPX4) signaling pathway." (PMID 38540711, 2024). "Western blot results showed that vitamin E could significantly reverse the decrease of the GPX4 expression level caused by sepsis and inhibit the occurrence of ferroptosis." (PMID 35910848, 2022). "GPX4 is not only a negative regulator of ferroptosis and has been associated with numerous cancers, but it also helps to attenuate lipid peroxidation, inflammasome activation, and pyroptosis in the context of sepsis." (PMID 36386841, 2022). "Western blot experiments showed that Fer-1 could significantly reverse the decrease of the GPX4 expression level caused by sepsis and inhibit the occurrence of ferroptosis." (PMID 35910848, 2022). "ACSL4 and GPX4 have strong diagnostic and differential diagnostic value in sepsis, including the ability to predict 28-day mortality in sepsis patients, and may become new potential serum markers for the diagnostic and differential diagnostic of sepsis." (PMID 40264754, 2025). "In this study, we observed that GPX4 expression was suppressed in the cardiac tissue of a CLP-induced mouse sepsis model, suggesting the occurrence of ferroptosis in the myocardial tissue." (PMID 40070882, 2025). "Clinical relevance for ferroptosis in septic lung injury remains under investigation, but accumulating data from small cohort studies indicate that sepsis patients with high serum iron levels and lower GPX4 activity show worse pulmonary outcomes." (PMID 40893878, 2025). "Studies have shown that modulating the Nrf2/GPX4 pathway can effectively intervene in ferroptosis death, intestinal inflammation, and mechanical barrier function in sepsis-induced intestinal injury, indicating the presence of ferroptosis in this context." (PMID 40723819, 2025). "For example, the NRF2 pathway inhibits ferroptosis and reduces sepsis-induced lung tissue damage by upregulating antioxidant proteins such as GPX4 and SLC7A11." (PMID 41250137, 2025).